PDGFRB (platelet derived growth factor receptor beta)
Diseases named in the same sentence as PDGFRB in open-access papers (continued):
Sharing a sentence is not in itself a finding about the gene and the disease.
chordoma (continued). "Our micro-array data revealed that a large number of genes were differentially expressed in chordoma tissues, including EGFR, PDGFRβ, IGF-1R and MET etc., which have been identified to the potential therapeutic targets in chordoma with both clinical and molecular evidence." (PMID 29348851, 2017). "Successively, in a molecular/biochemical analyses of the three receptors targeted by IM (PDGFRB, PDGFRA, and KIT) in a series of 31 chordoma patients, it was proven that PDGFRB was highly expressed and phosphorilated whereas PDGFRA and KIT were less expressed but equally activated." (PMID 20109225, 2010). "PDGFRB is overexpressed in malignant peripheral nerve sheath tumors (MPNST) and chordomas." (PMID 21171987, 2010).
renal fibrosis (35 papers, 2013 to 2025). A final common manifestation of a wide variety of chronic kidney diseases characterized by glomerulosclerosis and tubulointerstitial fibrosis. "PDGFB/PDGFRB signaling has been associated with fibrosis; for example, constitutive activation of PDGFRB in mesenchymal cells has been shown to result in spontaneous renal fibrosis, while inhibition of PDGFB or PDGFRB has reduced fibrosis in experimental CKD models." (PMID 40952790, 2025). "DJ-1 also acts as an oncogene and many tyrosine kinases such as PDGFRβ have been shown to be activated during oncogenesis to drive mTOR activity, which also plays important role in renal fibrosis." (PMID 39761275, 2025). "PDGFRβ is a potent marker of myofibroblasts, which are the primary source of extracellular matrix in renal fibrosis." (PMID 36804530, 2023). "The upregulation of PDGFRβ, a marker of mesenchymal cells, is a well-recognized characteristic of renal fibrosis." (PMID 35096904, 2021). "The relevance of PDGF signaling blockade has been shown to reduce renal fibrosis and more specifically PDGFRβ blockade aided by Imatinib mesylate treatment revealed a startling improvement in renal fibrosis." (PMID 33420132, 2021). "PDGFRB, indicating a potential mechanism for mesangial proliferation and renal fibrosis, was also expressed in fibroblasts." (PMID 33936064, 2021). "It has recently been shown that both in animal models and in patients with renal fibrosis PDGFRβ is not only upregulated but also significantly strongly activated, i.e., phosphorylated." (PMID 35096904, 2021). "Recently, we studied anti-fibrotic effects of IFNγ and PEGylated IFNγ (PPB-PEG-IFNγ) targeted to PDGFRβ-expressing myofibroblasts in an animal model of renal fibrosis." (PMID 26112172, 2015). "We hypothesized that DJ-1 may cooperate with PDGFRβ to activate mTORC1 in the accumulation of matrix proteins during the progression of renal fibrosis." (PMID 39761275, 2025). "By employing bioinformatics, improved biochemical methods, and advanced genetic engineering tools, our research group has demonstrated that Meis1 was able to attenuate renal fibrosis by regulating Ptprj/PDGFRβ pathway to inhibit fibroblast proliferation and activation." (PMID 39162106, 2024). "Ptprj knockdown increased the phosphorylation of PDGFRβ levels in fibrotic kidneys compared with that in the controls, which suggests that Ptprj may regulate renal fibrosis through PDGFRβ." (PMID 39162106, 2024). "The limitation of our study is that whether the effect in our study of Meis 1 regulating Ptprj to improve renal fibrosis depended solely on its inhibitory effects on mitogenic signals such as PDGFRβ remains to be determined." (PMID 39162106, 2024). "The increased expression of interstitial PDGFRβ was used to describe the distribution of pericytes and myofibroblasts and could attenuate the renal fibrosis by blocking it." (PMID 34671682, 2021). "Therefore, we identify an important role of DJ-1/PTEN/PDGFRβ/mTORC1 axis in driving renal fibrosis." (PMID 39761275, 2025). "SRT1720, a potent activator of SIRT1, promotes renal fibrosis via increased phosphorylation of epidermal growth factor receptor (EGFR) and platelet-derived growth factor receptor β (PDGFRβ)." (PMID 39335456, 2024). "The development of renal fibrosis is not only dependent on the activation of EGFR and PDGFRβ signaling pathways, but also on TGF-β pathways." (PMID 36139886, 2022). "The immunofluorescence staining for fibronectin and PDGFRβ and Sirius red staining indicated that treatment with DKK1 or mitoQ could ameliorate renal fibrosis in d‐gal‐treated mice." (PMID 31318148, 2019). "Our finding could be supported by the recent report that selective disruption of TGF-βR2 in renal PDGFRβ+ cells preserves EPO production but no discernible effect on myofibroblast markers in the murine model of renal fibrosis." (PMID 34724959, 2021).
renal fibrosis (continued). "We also examined FSTL1 expression in kidneys from patients with immunoglobulin A nephropathy at grade III, or membranous nephropathy at grade II, which had developed renal fibrosis (data not shown), and found colocalization of FSTL1 with PDGFRβ." (PMID 35525270, 2022).
sarcoma (35 papers, 2011 to 2025). A usually aggressive malignant neoplasm of the soft tissue or bone. "PDGFRB has been also disclosed to promote cancer stem cell phenotypes and epithelial-mesenchymal transition in sarcomas." (PMID 33731124, 2021). "This present study is the first report describing the in vitro and in vivo efficacy of MGCD516, a novel, broad spectrum small molecule inhibitor that blocks a wide array of RTKs known to be amplified/overexpressed in sarcomas, including c-Kit, PDGFRβ, PDGFRα, c-Met, and Axl." (PMID 26675259, 2016). "Finally, as a standard of care drug in sarcoma and renal carcinoma pazopanib is dosed daily and would thus be likely to block any compensatory survival signaling through PDGFRα/PDGFRβ/FGFR, but not through c-MET or SRC-linked cytokine receptors." (PMID 28146421, 2017). "Among them, COL1A1, PDGFRB, and SPARC were confirmed as sarcoma-related genes using the GEPIA database." (PMID 41040657, 2025). "Long shown to be expressed and active in Ewing sarcoma, PDGFRB and autocrine and paracrine feedback loops with its ligand PDGFB (platelet-derived growth factor beta) contribute to sarcoma cell proliferation and migration." (PMID 29776413, 2018). "The most common RTKs with high basal expression levels in the sarcoma cell lines tested were IGF1-R, c-Kit, c-Met and PDGFRb." (PMID 26675259, 2016). "Through this analysis, COL1A1, PDGFRB, and SPARC were identified as sarcoma-related genes." (PMID 41040657, 2025).
osteosarcoma (32 papers, 2006 to 2026). A usually aggressive malignant bone-forming mesenchymal neoplasm, predominantly affecting adolescents and young adults. "Studies have demonstrated that PDGFRα and PDGFRβ are expressed in a significant percentage of osteosarcoma samples, and their activation is associated with increased tumor growth and metastasis." (PMID 40283955, 2025). "PDGFRB encodes a cell-surface tyrosine kinase receptor that, in osteosarcoma HOS cells, drives aerobic glycolysis through the PI3K/AKT/mTOR/c-Myc pathway while preserving ΔΨm." (PMID 41040657, 2025). "We further validated these candidates via the GEPIA database, narrowing down to COL1A1, PDGFRB, and SPARC as the most significantly associated with osteosarcoma progression." (PMID 41040657, 2025). "and found that PDGFD was mainly expressed in osteosarcoma cells, while the PDGFRB expression was observed in both osteosarcoma cells and stromal cells." (PMID 38652223, 2024). "The distribution of PDGFD and PDGFRB in osteosarcoma were consistent with their distribution in Rhabdomyosarcoma." (PMID 38652223, 2024). "In order to assess the effect of USP4 and USP17 on PDGFRβ stability, we transiently overexpressed USP4 and USP17L22 in U2OS osteosarcoma cells that naturally express PDGFRβ." (PMID 35064336, 2022). "The therapeutic relevance of PDGFRβ in canine cancers is further supported by the efficacy of treatment with RTK inhibitors (TKIs) such as toceranib phosphate, which targets PDGFRβ among other kinases, for various canine malignancies, including mast cell tumors, osteosarcoma, and thyroid carcinoma." (PMID 41472102, 2025). "In order to explore whether TRIM21 can act as an E3 ligase for PDGFRβ, we depleted human osteosarcoma cells (U2OS) of TRIM21 using siRNA." (PMID 37175489, 2023). "In conclusion, osteosarcoma with high expression of VEGFR2, PDGFRβ and CD31 is more sensitive to anlotinib." (PMID 39618078, 2024). "Our findings indicated that anlotinib selectively inhibited osteosarcoma with high expression of VEGFR2, PDGFRβ or CD31." (PMID 39618078, 2024). "In conclusion, anlotinib inhibited the growth of osteosarcoma PDX models by varying degrees depending on the expression levels of VEGFR2, PDGFRβ and CD31." (PMID 39618078, 2024). "Histology results suggested that anlotinib significantly inhibited the growth of osteosarcoma by inducing mitotic arrest, necrosis and apoptosis, and selective against tumors with high expression of VEGFR2, PDGFRβ and CD31." (PMID 39618078, 2024). "Deubiquitination of PDGFRβ mediated by USP17 and USP4 leads to dysregulated downstream signaling of STAT3 transduction and transcription, impacting osteosarcoma cell proliferation." (PMID 39062505, 2024). "We report here that another E3 ligase, i.e., tripartite motif-containing protein 21 (TRIM21), contributes to the ubiquitination of PDGFRβ in human primary fibroblasts AG1523 and the osteosarcoma cell line U2OS and regulates basal levels of PDGFRβ." (PMID 37175489, 2023). "Pazopanib molecular targets (c-KIT-CD117, FGFR2-3 PDGFRα-β, VEGFR-1-2, and -3) displayed a plasma membrane heterogeneous degree of expression in seven osteosarcoma cell lines, with FGFR2, VEGFR3, and PDGFRβ represented most." (PMID 32531992, 2020). "Growth factors and receptors FGF2, IGF1R, PDGFRB and TGFA were identified as factors contributing selectively to the control of U2OS osteosarcoma and HCT116 colon cancer cell growth." (PMID 24023735, 2013). "Our findings suggest that COL1A1, PDGFRB, and SPARC may be involved in mtRNA-driven tumorigenesis and could serve as promising therapeutic targets for osteosarcoma." (PMID 41040657, 2025). "PDGFRB expression showed no significant variation between non-metastatic and metastatic osteosarcoma, nor strong correlations with survival times." (PMID 38652223, 2024).
osteosarcoma (continued). "The differing positive rate of PDGFRB between non-metastatic osteosarcoma primary lesions and metastatic primary lesions was not statistically significant (54.44% ± 33.86% vs. 29.44% ± 30.87%, p = 0.1212)." (PMID 38652223, 2024). "IHC was used to detect PDGFD and PDGFRB expression in non-metastatic and metastatic osteosarcoma primary lesions." (PMID 38652223, 2024). "Finally, PDGFRα, Axl, PDGFRβ, RYK, EGFR, EphA2, EphA10 and IGF1-R are key targets of imatinib mesylate in osteosarcoma." (PMID 24599309, 2014). "Additionally, organoids of both non-metastatic and metastatic osteosarcoma were constructed, and immunohistochemistry and multicolor immunofluorescence techniques were employed to validate the distributional characteristics, expression, and ligand-receptor binding of PDGFD and PDGFRB." (PMID 38652223, 2024).
atherosclerosis (30 papers, 2007 to 2025). A disease characterized by the build-up of fatty material and calcium deposition in the arterial wall resulting in partial or complete occlusion of the arterial lumen. "We focused on Stat1 (Signal Transducer and Activator of Transcription-1) due to its involvement in Pdgfrβ signaling in several disease states such as atherosclerosis and Kosaki overgrowth syndrome." (PMID 37002214, 2023). "Overall, the results of these studies reveal that in VSMCs, LRP1 plays a major role in maintaining the integrity of the vascular wall and reducing atherosclerosis by suppressing the PDGFRβ and TGFβ signaling pathways." (PMID 34124208, 2021). "Studies from our laboratory have shown that LRP1 suppresses PDGF receptor β (PDGFRβ) activation and protects against atherosclerosis." (PMID 19742316, 2009). "Low density lipoprotein receptor-related protein 1 (LRP1) protects against atherosclerosis by regulating the activation of platelet-derived growth factor receptor β (PDGFRβ) in vascular smooth muscle cells (SMCs)." (PMID 19742316, 2009). "Therefore, we need to continue to explore the mechanism of CDCP1’s influence on PDGFRβ endocytosis and intimal hyperplasia from multiple perspectives in order to provide a new treatment strategy for atherosclerosis in the future." (PMID 40256729, 2025). "In this study, the gain-of-function knock-in in PDGFRβ locus (PDGFRβD849V) in mice results in the exacerbation of atherosclerosis including the increase of inflammatory cell migration, the promotion of the proliferation of SMCs and the facilitation of the plaque formation." (PMID 32433495, 2020). "Tight regulation of the PDGFRβ is critical, as excessive activation induces tumor formation and in the vasculature contributes to the development of occlusive vascular disease, such as atherosclerosis and restenosis." (PMID 23922991, 2013). "Selective elimination of PDGFRβ-dependent PI3K activation thus could be a potential therapeutic target for both atherosclerosis and Marfan syndrome." (PMID 19742316, 2009). "Thus, regulation of PI3 Kinase by PDGFRβ is essential for maintaining vascular integrity, and for the prevention of atherosclerosis as well as Marfan syndrome." (PMID 19742316, 2009). "Our findings thus suggest that abnormal activation of PDGFRβ signaling, which has so far not been reported in MFS, is the major mediator of the increased atherosclerosis in the smLRP− mice, and that increased PDGFRβ activity is brought about by two independent and synergistic mechanisms." (PMID 17505534, 2007). "Thus, rosiglitazone (as a Smad/TGFβ antagonist) and Gleevec (as a PDGFRβ inhibitor) act at different steps in a linear sequence of events that result in a Marfan-like syndrome and culminate in extensive atherosclerosis in smLRP− artery walls." (PMID 17505534, 2007). "A direct implication of PDGFRβ signaling in local leucocyte accumulation, VSMC dedifferentiation and inflammation has also been demonstrated in a model of atherosclerosis." (PMID 27513343, 2016). "A recent study of PDGF/PDGFRβ signalling in VSMCs revealed that activation of this pathway increased inflammation but not atherosclerosis under a normal cholesterol level." (PMID 28699690, 2017).
myeloproliferative neoplasm (30 papers, 2006 to 2026). A clonal hematopoietic stem cell disorder, characterized by proliferation in the bone marrow of one or more of the myeloid (i.e., granulocytic, erythroid, megakaryocytic, and mast cell) lineages. "This gene has been associated with myeloproliferative disorders, as shown by its fusions with platelet-derived growth factor receptor beta gene (PDGFRB)." (PMID 32098292, 2020). "This case report has certain limitations, particularly in terms of generalizability—for example, the possibility of a pre-existing myeloproliferative neoplasm (MPN) with adverse mutations preceding the acquisition of the PDGFRB rearrangement cannot be excluded." (PMID 41278291, 2025). "The differential diagnosis for IHES includes primary HES associated with myeloproliferative neoplasms, such as those with genetic mutations in PDGFRA, PDGFRB, FGFR1, and JAK2." (PMID 39867100, 2024). "Other fusion mutations observed in children with myeloproliferative disorders with the use of next-generation sequencing technologies include ALK, ROS1, FIP1L1::RARA, HCMOGT1::PDGFRB, NDEL1::PDGFRB, and NUP98::HOXA11." (PMID 39682300, 2024). "Several rare gene fusions involving PDGFRβ have been described in patients with chronic myeloproliferative disorders (MPD), myelodysplastic/myeloproliferative syndromes (MDS/MPD) and AML." (PMID 36474285, 2022). "For example, the score between Budd-Chiari (MIM: 600880) syndrome and Myeloproliferative disorder (MIM: 131440) is in the 97th percentile and genes associated to these diseases have in vivo verified first-level interactions (JAK2 – PDGFRB)." (PMID 26631976, 2015). "CEP85L was recently discovered to be the 5′ partner of a rearrangement involving PDGFRB in a patient with precursor T-ALL and an associated myeloproliferative neoplasm." (PMID 23637631, 2013). "Abnormality of PDGFRB gene is associated with chronic myeloid leukemia (CML), acute myelogenous leukemia (AML), chronic myelomonocytic leukemia (CMML), acute lymphocytic leukemia (ALL), chronic eosinophilic leukemia (CEL), myeloproliferative disease (MPD), and other diseases." (PMID 33663081, 2021). "PDGFRB rearrangement has been reported in a number of patients with CEL, B‐acute lymphoblastic leukemia, and myeloproliferative neoplasms with neutrophilia and/or monocytosis." (PMID 30697976, 2019). "Platelet‐derived growth factor receptor beta (PDGFRB) rearrangement has been reported in a number of patients with chronic eosinophilic leukemia (CEL), B‐acute lymphoblastic leukemia, myeloproliferative neoplasms, and juvenile myelomonocytic leukemia." (PMID 30697976, 2019). "The lymphoma associated oncogene NPM/ALK significantly altered the expression of 91phosphopeptides whilst the myeloproliferative disorder oncogenes BCR/ABL, TEL/PDGFRβ, Kit D816V, and Fip1L/PDGFRα changed the expression of 94, 114, 111 and 68 respectively." (PMID 22745689, 2012). "Molecular cytogenetic analysis (FISH) for PDGFRA, PDGFRB, and FIP1L1 rearrangements returned negative, effectively ruling out an underlying myeloproliferative neoplasm." (PMID 40943043, 2025). "This explains the lack of clinical and morphologic changes typically seen in PDGFRβ-related myeloproliferative disease." (PMID 36474285, 2022). "Moreover, imatinib inhibits the activity PDGFRβ and suppresses that of TEL-PDGFRβ, which is a fusion tyrosine kinase generated in chronic myeloproliferative diseases." (PMID 30344924, 2018). "Genetic testing excluded acute myeloid leukemia, myeloproliferative neoplasms, myelodysplastic syndromes, systemic mastocytosis, and myeloid/lymphoid neoplasms with eosinophilia, as results for PDGFRA, PDGFRB, FGFR1, or PCM1-JAK2 rearrangements were negative." (PMID 39867100, 2024). "We report a case of a rare PDGFRB rearrangement with SPTNB1 (spectrin beta, nonerythrocytic 1) that presented as atypical myeloproliferative neoplasm." (PMID 30377450, 2018).
myeloproliferative neoplasm (continued). "On fluorescent in-situ hybridization (FISH), myeloproliferative neoplasms (MPN) testing was negative for platelet-derived growth factor receptor-alpha (PDGFRA), platelet-derived growth factor receptor-beta (PDGFRB), and fibroblast growth factor receptor-1 (FGFR1) rearrangement." (PMID 32656011, 2020).